HSPA6 (heat shock protein family A (Hsp70) member 6)
Diseases named in the same sentence as HSPA6 in open-access papers (continued):
Sharing a sentence is not in itself a finding about the gene and the disease.
glioma (continued). "In order to further study the related pathway mechanism of HSPA6 in glioma cell lines, the differential gene pathway enrichment was analyzed by RNA sequencing after HSPA6 overexpression in the U251 cell line." (PMID 35281087, 2022). "Collectively, we demonstrated that HSPA6 may represent a new therapeutic target to improve the prognosis of patients with gliomas." (PMID 35281087, 2022). "Whether HSPA6 can be regarded as an effective target-therapeutic agent for glioma needs to be investigated further." (PMID 35281087, 2022). "In our study, we preliminarily explored that HSPA6 may affect the malignant degree of glioma cells through interaction with the PI3K-AKT signaling pathway." (PMID 35281087, 2022). "Interestingly, we found that the overexpression of HSPA6 accelerated the migration, proliferation, and invasion abilities of glioma cells." (PMID 35281087, 2022). "In our study, we explored the specific value of HSPA6 in glioma." (PMID 35281087, 2022). "Collectively, these results suggested that HSPA6 may be an independent but poor prognostic biomarker for patients with glioma." (PMID 35281087, 2022). "Furthermore, functional in vitro experiments verified the effect of HSPA6 in glioma cells and its possible pathway mechanism." (PMID 35281087, 2022). "Therefore, it follows that a gaining a more enhanced understanding of the correlation between HSPA6 and immunity will inevitably yield new concepts for immunotherapy in patients with glioma." (PMID 35281087, 2022). "Collectively, these results indicated that HSPA6 may influence the degree of malignancy in glioma cells by interacting with PI3K-AKT signaling pathway." (PMID 35281087, 2022). "However, the opposite effect was observed following the knockdown of HSPA6 in glioma cells." (PMID 35281087, 2022). "Moreover, univariate and multivariate Cox regression analysis showed that HSPA6 may represent a poor but independent prognostic biomarker for glioma." (PMID 35281087, 2022). "However, the functional effect of HSPA6 in the progression of glioma remains unclear." (PMID 35281087, 2022). "HSPA6 protein belongs to the HSP70 family; However, the biological function of this protein in gliomas has yet to be evaluated." (PMID 35281087, 2022). "Therefore, we hypothesized that HSPA6 may be a reliable prognostic biomarker for gliomas." (PMID 35281087, 2022).
cervical cancer (3 papers, 2017 to 2023). A primary or metastatic malignant neoplasm involving the cervix. "Moreover, hypermethylation of LYPD2 and SHE were associated with poor overall survival (OS); hypermethylation of FGF8 and HSPA6 were associated with poor progression free survival (PFS) in patients with cervical cancer." (PMID 29029430, 2017). "For example, bladder and cervical cancer tumour cell growth, migration, and invasion could be inhibited by increasing the expression of HSPA6." (PMID 36927457, 2023).
colon cancer (3 papers, 2021 to 2025). "Additionally, the reduced expression of HSPA6 in human colon cancer cell lines was found to lead to cell death through proteasome inhibition." (PMID 40765077, 2025).
lung adenocarcinoma (3 papers, 2019 to 2021). A carcinoma that arises from the lung and is characterized by the presence of malignant glandular epithelial cells. "According to The Cancer Genome Atlas lung adenocarcinoma (TCGA-LUAD) data, we found that multiple LSLC markers such as S100A9, HSPA6, and FAM83A were associated with a poor prognosis in lung adenocarcinoma patients." (PMID 34127680, 2021). "The present study first demonstrated that HSPA6 gene was overexpressed in lung adenocarcinoma tissues." (PMID 32508044, 2020). "We furthermore evaluated gene expression of HSPA6 in patients with lung adenocarcinoma and found that HSPA6 gene overexpressed in lung adenocarcinoma tissue, as compared to the adjuvant normal tissue (P < 0.01)." (PMID 32508044, 2020). "Treatment with HSP90 inhibitors of lung adenocarcinoma cell lines, as expected, showed remarkable changes in the homeostasis of HSPs, leading to deregulation of HSP90, HSP70, HSP60, HSC71, HSP70 protein 6 (HSPA6), and mitochondrial HSP70 (mitHSP70)." (PMID 31370342, 2019).
malaria (3 papers, 2016 to 2024). Malaria is a serious and sometimes fatal disease caused by a parasite that commonly infects a certain type of mosquito which feeds on humans. "Other genes previously associated with malaria pathogenesis, GZMB, FOS and HSPA6, were also higher among severe cases." (PMID 26961973, 2016). "HSPA6 expression has also been previously implicated in malaria pathogenesis, although it has never been considered when studying the severe versus uncomplicated phenotype." (PMID 26961973, 2016). "Differentially expressed probes form these canonical pathways that were previously shown to play a role in severe malaria pathogenesis were TLR2, TLR4, TLR8, HSPA6, CR1, C1qA, C1qB, C1qC, FOS, and GZMB." (PMID 26961973, 2016). "Of the remaining probes, four were in three genes, HSPA6, TLR8 and FOS, previously identified in experiments for malaria severity in human or murine systems." (PMID 26961973, 2016). "The higher expression of the TLR genes, GZMB, FOS, HSPA6, and CR1, in uncomplicated malaria cases during the late convalescence time point can be interpreted two ways." (PMID 26961973, 2016). "Of relevance to the role of HSPs in human malaria pathogenesis, transcripts for HSP60 (HSPD1) were down-regulated in SMA (log2FC = −0.81), as were HSP70 family members: HSPA1A (−1.31), HSPA1B (−0.99), HSPA4 (−0.33), HSPA4L (−0.68), HSPA5 (−0.51), and HSPA6 (−0.81)." (PMID 39452740, 2024).
melanoma (3 papers, 2013 to 2021). A malignant, usually aggressive tumor composed of atypical, neoplastic melanocytes. "Among up-regulated HSPs, HSPA6 is the most over-expressed transcript in melanoma treated cells with a FC value of 368.61." (PMID 23642048, 2013).
Alzheimer disease (2 papers, 2018 to 2022). A progressive, neurodegenerative disease characterized by loss of function and death of nerve cells in several areas of the brain leading to loss of cognitive function such as memory and language. "A recent study reported the role of HSPA6 in SH-SY5Y neuronal cells which are used as a model system for neurodegenerative diseases such as Alzheimer’s disease and PD." (PMID 29653596, 2018). "In addition, a previous study indicated that Parkinson’s disease and Alzheimer’s disease (AD) led to 30.4-fold and 6.3-fold increases, respectively, in HSPA6 expression." (PMID 35205234, 2022).
atherosclerosis (2 papers, 2022 to 2025). A disease characterized by the build-up of fatty material and calcium deposition in the arterial wall resulting in partial or complete occlusion of the arterial lumen. "A study confirmed the association between high HSPA6 expression and the progression of atherosclerosis." (PMID 40765077, 2025). "HSPA6 is also a putative target of endothelial nitric oxide synthase and is involved in the highly clinically relevant inhibition of vascular smooth muscle cell (VSMC) proliferation, which can repair vessels in human atherosclerosis." (PMID 35706446, 2022).
COVID-19 (2 papers, 2023 to 2025). A disease caused by infection with severe acute respiratory syndrome coronavirus 2. "Overlapping genes for TSA and COVID-19 were SERPINH1, LPAR1, and TCEA2, and overlapping genes for TSA and MDD were NOL3, LPAR1, and HSPA6." (PMID 40918512, 2025). "The HSPA6 gene is considered a hub gene in SARS-CoV-2 infection and can differentiate remdesevir-treated COVID-19 patients." (PMID 38003837, 2023).
Arrhythmia (1 paper, 2025). Any cardiac rhythm other than the normal sinus rhythm. "The negative correlation with PABPC1, involved in mRNA stability, suggested translational stress in arrhythmia-associated macrophages, further supported by concurrent HSPA6 upregulation." (PMID 40900730, 2025). "HSPA6 mutations affected domains essential for ATPase activity, potentially impairing stress response functions —particularly relevant given its correlation with CCR2 in arrhythmia-associated macrophages." (PMID 40900730, 2025).
Arthritis (1 paper, 2019). Inflammation of a joint. "However, the SDN map identified five cSABPs (ENO1, FTL, IMMT, PDCD6IP and HSPA6) that were associated with various types of arthritis." (PMID 31511554, 2019).
brain cancer (1 paper, 2016). A primary or metastatic malignant neoplasm affecting the brain. "Interestingly, higher HSPA6 (the gene most strongly induced by IER5 expression) expression is also related to poorer prognosis, and we observed overall similar patterns of survival among bladder and brain cancer patients exhibiting high versus low IER5 and HSPA6 expression." (PMID 26754925, 2016).
brain glioma (1 paper, 2022). A malignant glioma that involves the brain. "In addition, human brain glioma cells (U251) were normally infected with 1MOI of EV71, and the expression of HSPA6 mRNA in the cells was also found to be upregulated." (PMID 35308396, 2022).
cervical squamous cell carcinoma (1 paper, 2022). A squamous cell carcinoma arising from the cervical epithelium. "HSPA6 was found to be involved in the development of cervical squamous cell carcinoma as an antigen processing and presentation gene." (PMID 35281087, 2022).
congenital heart disease (1 paper, 2023). A heart disease that is present at birth. "This strengthens our belief that ROR2 regulates HSPA6 expression through the β‐catenin/SOX3 signalling pathway, providing some clinical implications for treating TOF in congenital heart disease." (PMID 37749917, 2023).
gastric tumor (1 paper, 2021). "We also found that ARHGEF10L expression stimulated HSPA6 expression in SGC7901 cells that were derived from gastric tumors." (PMID 33833821, 2021). "Since we reported that ARHGEF10L played a role through RhoA-ROCK1-ERM signaling, an important pathway in tumorigenesis, and stimulated EMT and HSPA6 expression in liver tumors and gastric tumor cells, we suggest that ARHGEF10L is a novel oncogene in many tumors." (PMID 33833821, 2021). "The current study and a study with gastric tumor cells used RNA sequencing to investigate the downstream mechanism of ARHGEF10L and found increased HSPA6 expression in ARHGEF10L-expressing HeLa cells." (PMID 33833821, 2021).
glioblastoma (1 paper, 2022). The most malignant astrocytic tumor (WHO grade IV). "Quantitative protein analysis confirmed that HSPA6 was expressed at high levels in patients with glioblastoma." (PMID 35281087, 2022).
Insulin resistance (1 paper, 2022). Increased resistance towards insulin, that is, diminished effectiveness of insulin in reducing blood glucose levels. "Furthermore, HSPA6/7 are chaperone proteins of the heat shock family, which may enhance metabolic profiles in skeletal muscle and serve as a defense system against insulin resistance and T2D." (PMID 35204022, 2022).
keratoconus (1 paper, 2022). A degenerative, structural disorder of the eye, characterized by a cone-shaped protrusion of the cornea. "Among the proteins identified in exosomes, frequently accepted markers of nanovesicles such as CD81 and various Hsp70 species were found, including HSPA2 in both types of exosomes, HSP1B in healthy ones, and HSPA5 and HSPA6 in keratoconus." (PMID 36289615, 2022).
liver fibrosis (1 paper, 2021). "In the present study, the results of the protein microarray showed that autoantibodies to CENPF, ACY1, ENO1, and HSPA6 may have underlying detection values for liver fibrosis staging." (PMID 35059422, 2021). "Owing to lack of availability of HSPA6 protein, we only validated the diagnostic performance of autoantibodies to CENPF and ACY1 for liver fibrosis staging by ELISA." (PMID 35059422, 2021).
mastitis (1 paper, 2022). Inflammation of breast tissue during lactation or postpartum due to an obstructed duct or infection. "The HSPA6 is also significantly upregulated in circulating leucocytes of clinical mastitis, but not in the subclinical mastitis." (PMID 35812870, 2022).
myeloma (1 paper, 2023). "High expression of both HMOX1 and HSPA6 correlated positively with overall survival of myeloma patients." (PMID 37895838, 2023). "We found that carfilzomib upregulated the expression of several genes related to UPR, including HSPA6 and HMOX1, in myeloma cell lines." (PMID 37895838, 2023). "The relationship between the expression levels of HSPA6 or HMOX1 genes and prognosis of myeloma patients treated with proteasome inhibitors was assessed using gene expression data and clinical information obtained from the public database (GSE9782)." (PMID 37895838, 2023). "We found that carfilzomib upregulated the expression of several genes related to UPR, such as HSPA6 (heat shock protein family A (Hsp70) member 6) and HMOX1 (hemo oxygenase 1), in myeloma cell lines." (PMID 37895838, 2023).
neuroblastoma (1 paper, 2023). Neuroblastoma (NB) is the most common solid, extracranial childhood tumor. "We calculated the pairwise correlation coefficients for HSPA6 and HSPH1 co-expression in neuroblastoma SH-SY5Y and differentiated SH-SY5Y cells." (PMID 36979108, 2023).
pancreatic cancer (1 paper, 2024). "Among them, pancreatic cancer cells in the cluster 8 with TIMP1+/FN1+ showed the strongest resistance, while the cluster 1 with CLDN18-/CEACAM5- and the cluster 7 with HSPA6+/NEAT1+ showed milder resistance." (PMID 38343537, 2024).
prostate carcinoma (1 paper, 2023). A carcinoma that arises from epithelial cells of the prostate gland. "Few studies have addressed the role of WA on the expression of Hsps in cancer cells, with one study supporting that WA treatment led to upregulation of Hsp70 and HspA6 in prostate cancer cells, protecting against programmed cell death." (PMID 36701406, 2023).
pulmonary TB (1 paper, 2026). "Upregulated proteins in HSP macrophages included those encoding for Hsp70 family proteins (e.g., HSPA1A, HSPA1B, HSPA6, and HSPA8), which are known to modulate NF-κB–mediated release of pro-inflammatory cytokines from alveolar macrophages in pulmonary TB." (PMID 41489684, 2026).
respiratory failure (1 paper, 2025). The significant impairment of gas exchange within the lungs resulting in hypoxia, hypercarbia, or both, to the extent that organ tissue perfusion is severely compromised. "Regarding the associations between HSPs SNPs and respiratory failure indicators, we found that rs6457452 HSPA1B (p = 0.03) and rs753856 HSPA6 (p = 0.02) were linked to prolonged oxygen therapy, whereas rs706121 BAG1 (p = 0.04) decreased the duration of lug ventilation, indicating a better prognosis." (PMID 41009536, 2025).
rhabdomyosarcoma (1 paper, 2022). A rare aggressive malignant mesenchymal neoplasm arising from skeletal muscle. "We reported that host heat shock protein A6 (HSPA6) was induced by EV71 infection and involved infection in both Rhabdomyosarcoma (RD) cells and neurogliocytes." (PMID 35308396, 2022).
schizophrenia (1 paper, 2016). A major psychotic disorder characterized by abnormalities in the perception or expression of reality. "The schizophrenia specific module, SCH_only_M7, was not correlated with any covariates we tested and contained 76 genes with BAG3, DNAJB1,DNAJB4, HSPAH and HSPA6 the top 5 hub genes in this module." (PMID 27898074, 2016).
thrombosis (1 paper, 2026). "Future studies should validate the roles of curcumin and HSPA6 in more complex in vivo models, such as hindlimb ischemia or arterial thrombosis, which would also facilitate the translation of our findings." (PMID 41502827, 2026).
thyroid cancer (1 paper, 2023). "In this study, biological information analysis identified four genes, HSPA6, FLNC, CLDN2, and E2F1 as candidate biomarkers of thyroid cancer." (PMID 37063290, 2023).
cancer (36 papers, 2014 to 2026). A tumor composed of atypical neoplastic, often pleomorphic cells that invade other tissues. "HSPA6 expression has been reported in certain tumor types and associated with outcomes, although its precise role in cancer is not well understood." (PMID 39858470, 2025). "For example, in the HSP70 family, HSPA5 and HSPA6 were positively associated with the hypoxia score in 23 and 20 cancers, respectively, while HSPA1L was negatively associated with hypoxia in 19 cancers." (PMID 33225964, 2020). "Thus, according to the literature, CAIX and HSPA6 are closely associated with the metastasis of certain cancers." (PMID 40765077, 2025). "The two-way role of HSPA6 in tumor, acting as both a potential target for tumor inhibition and risk factor of tumor development and tumor progression, underscores the complexity of its functions in cancer biology." (PMID 38111587, 2023). "YTHDF2 and YBX2 have the capacity to collaborate on heat shock protein family A (Hsp70) member 6 (HSPA6) mRNA to regulate HSPA6 expression by modulating its stability, which regulates the survival and progression of cancer cells." (PMID 39904996, 2025). "The genes BLK, CDC247, CSK, IRF5, STAT1, STAT4, and TNIP1 are associated with AIDs, and CDC37, DDX6, HSPA6, MAPT, PPIB, STAT1, and STAT4 are associated with cancers." (PMID 40429780, 2025). "In the cancer microenvironment, the expression of HSPA6 is significantly upregulated, which is closely related to tumor cell survival, proliferation, and chemoresistance." (PMID 40959101, 2025). "The complexity of these interactions underscores the significance of HSPA6 in various biological processes of cancer." (PMID 40959101, 2025). "While the HSPA6 gene exerts inhibitory effects on these processes in certain malignancies, it seems to induce cancer progression in others." (PMID 38543002, 2024). "Recent studies have found that HSPA6 exhibits to inhibit tumorigenesis and tumor progression in some types of cancers but promotes it in others." (PMID 36458368, 2023). "HSPA6 is up‐regulated in GC (a) The expression of HSPA6 in different cancers from Oncomine database." (PMID 36458368, 2023). "HSPA6 exhibits to inhibit tumorigenesis and tumor progression in some types of cancers but promotes in others." (PMID 36458368, 2023). "In fact, recent studies have shown that HSPA6 is also involved in cancer progression, including that of lung cancer, triple-negative breast cancer (TNBC), and bladder cancer." (PMID 35205234, 2022). "HSPA2 and HSPA6 showed elevated gene expression in 9 and 10 out of 21 human cancers, respectively, which was predictive of a lower overall survival for one cancer for each chaperone." (PMID 35311075, 2022). "In order to further verify the inhibitory effect of HSPA6 on cancer cell growth, we performed HSPA6 overexpression on HeLa cells with undetectable endogenous HSPA6." (PMID 34017687, 2021). "Although HSPA6 was discovered three decades ago, the functional roles in cancer progression are unclear." (PMID 34017687, 2021). "Experiments using ROS and nitrogen oxide synthase (NOS) inhibitors demonstrated the ROS- and reactive nitrogen species (RNS)-independent regulation of PTGER3 and HSPA6 when U937 cancer cells were treated with CAP." (PMID 32947888, 2020). "HSPA6 has been studied in human neuronal cells and cancer cell lines." (PMID 40765077, 2025). "Latest researches imply that the up-regulation of HSPA6 relates to drug response in cancer therapy." (PMID 36597133, 2023). "This discrepancy may arise from the multifaceted functions of HSPA6, affecting different aspects of cancer biology." (PMID 38111587, 2023). "However, the signaling pathway and mechanism of HSPA6 are still unclear in the field of cancer research." (PMID 35281087, 2022).